P2RX5 (purinergic receptor P2X 5)
Description:
[Isoform 6]: ATP-gated nonselective transmembrane cation channel permeable to potassium, sodium and calcium. Unlike other P2RX receptors, the P2X5 receptor is also permeable to chloride. May play a supporting role in the inflammatory response (By similarity). [Isoform 1]: Non-functional.
Synonyms: P2X5; LRH-1; P2X5R
Tractability: Small molecule: it belongs to a druggable protein family. Antibody: UniProt places it where antibodies can reach, with high confidence; its Gene Ontology location is reachable by antibodies, with high confidence; UniProt predicts a signal peptide or a membrane-spanning region; the Human Protein Atlas places it where antibodies can reach. PROTAC: ubiquitination databases record sites on it; a small molecule that binds it is known.
Target class: Ligand-gated ion channel; P2X receptor; Ion channel
Safety:
Unwanted effects reported when the protein is acted on. In parentheses: how it was acted on, where the effect was seen, and who reports it.
decreased convulsions (inhibition, acute dosing; nervous system, renal, immune; source: Lynch et al. (2017))
decreased inflammation (inhibition, acute dosing; nervous system, renal, immune; source: Lynch et al. (2017))
decreased pain (inhibition, acute dosing; nervous system, renal, immune; source: Lynch et al. (2017))
hemolysis (activation, acute dosing; nervous system, renal, immune; source: Lynch et al. (2017))
increased pain (activation, acute dosing; nervous system, renal, immune; source: Lynch et al. (2017))
increased urinary sodium excretion (activation, acute dosing; nervous system, renal, immune; source: Lynch et al. (2017))
increased urine excretion (activation, acute dosing; nervous system, renal, immune; source: Lynch et al. (2017))
neurodegeneration (activation, chronic dosing; nervous system, renal, immune; source: Lynch et al. (2017))
Gene: Protein-coding gene on chromosome 17 (3,672,199 to 3,696,398, reverse strand). Ensembl gene ENSG00000083454.
Subcellular location: Cell membrane (Isoform 6)
Subcellular location (Human Protein Atlas): Cytosol; Plasma membrane
Pathways (Reactome):
Hemostasis: Elevation of cytosolic Ca2+ levels; Platelet homeostasis
Gene Ontology:
Molecular function: ATP-gated ion channel activity; ligand-gated monoatomic anion channel activity; ATP binding; extracellularly ATP-gated monoatomic cation channel activity; monoatomic ion channel activity; purinergic nucleotide receptor activity; transmembrane signaling receptor activity; identical protein binding; voltage-gated monoatomic ion channel activity
Biological process: chloride transport; calcium ion transmembrane transport; nervous system development; osteoclast maturation; positive regulation of calcium ion transport into cytosol; positive regulation of calcium-mediated signaling; signal transduction; excitatory postsynaptic potential; monoatomic anion transmembrane transport; monoatomic cation transmembrane transport; monoatomic ion transport; positive regulation of calcium ion import across plasma membrane; purinergic nucleotide receptor signaling pathway; regulation of skeletal muscle tissue regeneration; response to ATP; response to calcium ion; response to pH; response to zinc ion
Cellular component: plasma membrane; membrane; postsynapse
Genetic constraint (gnomAD): Loss-of-function variants: 39 observed, 47.58 expected, observed/expected ratio (o/e) 0.82, 90% interval 0.63 to 1.07. The upper end of that interval is the gene's LOEUF score, 1.07, which puts it in group 4 of 6, group 1 being the genes least tolerant of losing a copy. Missense variants: 531 observed, 532.22 expected, observed/expected ratio (o/e) 1, 90% interval 0.93 to 1.07. Synonymous variants: 217 observed, 223.17 expected, observed/expected ratio (o/e) 0.97, 90% interval 0.87 to 1.09.
Homologues: Orthologues: chimpanzee P2RX5 (99% identical), macaque P2RX5 (82% identical), guinea pig P2RX5 (74% identical), dog P2RX5 (73% identical), pig P2RX5 (69% identical), mouse P2rx5 (69% identical), rat P2rx5 (69% identical), tropical clawed frog p2rx5 (61% identical), rabbit P2RX5 (57% identical), zebrafish p2rx5 (48% identical), zebrafish p2rx8 (39% identical). Paralogues in human: P2RX4 (44% identical), P2RX6 (42% identical), P2RX3 (40% identical), P2RX2 (38% identical), P2RX1 (37% identical), P2RX7 (32% identical).
Diseases named in the same sentence as P2RX5 in open-access papers:
P2RX5 is named in the same sentence as 32 diseases in open-access papers, as found by Europe PMC text mining. Sharing a sentence is not in itself a finding about the gene and the disease. The quoted sentences say what the papers report.
periodontitis (4 papers, 2018 to 2026). An acute or chronic inflammatory process that affects the tissues that surround and support the teeth. "Notably, the down-regulation of miR-1260b, miR-1224-5p, miR-3156-5p and miR-4286 may contribute to the progression of periodontitis by promoting the expression of NEDD9, P2RX5 and CSF1R." (PMID 41992052, 2026).
Obesity (2 papers, 2024 to 2025). Accumulation of substantial excess body fat. "Lastly, we unravel a previously unappreciated role for P2RX5 agonism to exert an anti-obesity effect in the presence of enhanced brown adipose tissue recruitment in male mice housed at thermoneutrality." (PMID 39484996, 2024). "On the other hand, in P2RX5 knockout mice, the purinergic stimulation was ineffective, and even the anti-obesity effect of the β3-AR agonist was blunted." (PMID 39484996, 2024).
chordoma (1 paper, 2023). Chordomas are rare malignant tumors arising from embryonic remnants of the notochord in axial skeleton. "The expression of AMOT, RYR3, P2RX5, and TNFSF14 were higher in recurrent chordomas than primary chordomas while NPTX1 was contrast." (PMID 38012562, 2023). "miR-186-5p, miR-125b-5p, miR-1260a, and their target protein mRNAs including AMOT, NPTX1, RYR3, P2RX5, TNFSF14 may be the basement of chordoma research." (PMID 38012562, 2023).
COVID-19 (1 paper, 2021). A disease caused by infection with severe acute respiratory syndrome coronavirus 2. "The proximity score of promethazine was significantly low partly by targeting genes including CALM1, KCNS1, LPAR4, LPAR6, P2RY12, P2PY8, and P2RX5, which were DEGs between T cell subsets of COVID-19 samples and healthy controls." (PMID 33919660, 2021).
Impaired glucose tolerance (1 paper, 2025). An abnormal resistance to glucose, i.e., a reduction in the ability to maintain glucose levels in the blood stream within normal limits following oral or intravenous administration of glucose. "Interestingly, global and brown adipocyte-specific P2rx5 deficiency is associated with impaired glucose tolerance in both lean and diet-induced obese mice, most likely due to it regulating glucose disposal into BAT depots." (PMID 40650249, 2025).
multiple myeloma (1 paper, 2020). "The P2RX5 gene is expressed in normal lymphocytes, B and T lineage ALL, a range of lymphoma and multiple myeloma cases, the CD34+ fractions of CML and AML, and possibly at low levels in brain and skeletal muscle, but there is minimal expression in GVHD target tissues (intestine, liver, lung, skin)." (PMID 32582592, 2020).
metabolic disease (1 paper, 2024). A congenital disorder (due to inherited enzyme abnormality) or acquired (due to failure of a metabolically important organ) disorder resulting from an abnormal metabolic process. "Altogether, our data support a role for P2RX5 in mediating brown adipocyte differentiation and function that could be further targeted for benefits in the context of adipose tissue pathology and metabolic diseases." (PMID 39484996, 2024).
P2RX5 also shares sentences with these, for which no sentence is quoted: cancer (10 papers); tumor (10); breast carcinoma (2); autism (1); Bladder (1); bladder cancer (1); brain cancer (1); diabetes (1); Duchenne muscular dystrophy (1); fibromyalgia (1); infection (1); inflammatory bowel disease (1); ischemia (1); ischemic stroke (1); leukaemia (1); lymphoid tumor (1); male infertility (1); neuroblastoma (1); pancreatitis (1); papillary carcinoma (1); periodontal disease (1); pheochromocytoma (1); prostate carcinoma (1); prostate tumour (1); renal cell carcinoma (1).